OR4X1 (olfactory receptor family 4 subfamily X member 1)
Description:
Odorant receptor.
Synonyms: OR11-104
Tractability: Antibody: UniProt places it where antibodies can reach, with medium confidence; UniProt predicts a signal peptide or a membrane-spanning region; its Gene Ontology location is reachable by antibodies, with medium confidence.
Gene: Protein-coding gene on chromosome 11 (48,263,861 to 48,264,778, forward strand). Ensembl gene ENSG00000176567.
Subcellular location: Cell membrane
Pathways (Reactome):
Sensory Perception: Expression and translocation of olfactory receptors
Gene Ontology:
Molecular function: olfactory receptor activity; G protein-coupled receptor activity
Biological process: detection of chemical stimulus involved in sensory perception of smell; G protein-coupled receptor signaling pathway
Cellular component: plasma membrane; membrane
Genetic constraint (gnomAD): Missense variants: 503 observed, 381.4 expected, observed/expected ratio (o/e) 1.32, 90% interval 1.23 to 1.42. Synonymous variants: 181 observed, 147.87 expected, observed/expected ratio (o/e) 1.22, 90% interval 1.08 to 1.38.
Homologues: Orthologues: rabbit OR4X1 (79% identical), rat Or4x5 (78% identical), dog OR4X1 (76% identical), mouse Or4x5 (65% identical). Paralogues in human: OR4X2 (60% identical), OR4B1 (58% identical), OR4S1 (56% identical), OR4S2 (56% identical), OR4C46 (54% identical), OR4C15 (54% identical), OR4C6 (53% identical), OR4C13 (53% identical), OR4C3 (53% identical), OR4A15 (52% identical), OR4C11 (52% identical), OR4C12 (52% identical), and 116 more.